CTLA4 (cytotoxic T-lymphocyte associated protein 4)
Diseases named in the same sentence as CTLA4 in open-access papers (continued):
Sharing a sentence is not in itself a finding about the gene and the disease.
cancer (continued). "Immune checkpoint inhibitors (ICIs) have become a widely adopted cancer therapy since the FDA’s approval of the first anti-cytotoxic T-lymphocyte-associated protein 4 (CTLA-4) monoclonal antibody in 2011." (PMID 41341585, 2025). "The occurrence of EMT in cancer cells can cause immune escape, so patients become insensitive to anti-CTLA-4 therapy." (PMID 40487392, 2025). "Among the checkpoints, programmed cell death protein 1 (PD-1), programmed death-ligand 1 (PD-L1), and cytotoxic T lymphocyte-associated antigen 4 (CTLA-4) are targets initially identified for ICI due to their involvement in immune responses to cancer." (PMID 41180369, 2025). "By expressing inhibitory receptors such as cytotoxic T lymphocyte-associated antigen-4 (CTLA-4) (which binds to CD80/86 derived from cancer cells) and PD-1, Tregs disrupt costimulatory signaling and suppress antitumor T-cell activity." (PMID 41320679, 2025). "Immunotherapeutic agents such as anti-programmed death-ligand 1 (PD-L1) and anti-cytotoxic T lymphocyte -associated protein 4 (CTLA-4) inhibitors have emerged as revolutionary cancer treatments." (PMID 40846966, 2025). "The PD-1/PD-L1 axis and cytotoxic T-lymphocyte-associated antigen-4 (CTLA-4) have emerged as key targets in the treatment of various cancers, including CRC, demonstrating significant clinical efficacy." (PMID 41112277, 2025). "Immune checkpoint inhibitors (ICIs), targeting inhibitory receptors such as Programmed cell death protein 1 (PD-1), Programmed death-ligand 1 (PD-L1) and Cytotoxic T-lymphocyte-associated protein 4 (CTLA-4), have revolutionised cancer therapy." (PMID 39883592, 2025). "Immune checkpoint inhibitors (ICIs), targeting the programmed cell death 1 receptor (PD-1)/programmed cell death ligand 1 (PD-L1) and cytotoxic T-lymphocyte-associated protein 4 (CTLA-4) pathways, have transformed cancer treatment." (PMID 40070833, 2025). "In conclusion, CTLA-4 gene polymorphisms have emerged as potential biomarkers for predicting both cancer risk and treatment outcomes in immunotherapy." (PMID 41244914, 2025). "IRs like Programmed Death-1 (PD-1) and Cytotoxic T-lymphocyte associated protein 4 (CTLA-4) have been utilized for cancer treatment using inhibitory monoclonal antibodies (mAbs)." (PMID 39981237, 2025). "The immune checkpoint inhibitors available for clinical use primarily target the programmed death 1/program death 1 ligand (PD-1/PD-L1) and cytotoxic T-lymphocyte-associated protein 4 (CTLA-4) to reprogram the immune system that has been evaded by cancer." (PMID 40565872, 2025). "James Allison and Tasuku Honjo’s discoveries of cytotoxic T-lymphocyte-associated protein 4 (CTLA-4) and programmed cell death protein 1 (PD-1), respectively, opened new avenues for cancer immunotherapy." (PMID 40352591, 2025). "Several cancer types can be effectively treated with immune checkpoint inhibitors (ICIs), which are antibodies against cytotoxic T-lymphocyte-associated protein 4 (CTLA-4) or programmed death 1 (PD-1)." (PMID 40863204, 2025). "Immune checkpoint inhibitors (ICIs) represent a significant advance in cancer treatment, targeting molecules such as programmed cell death 1 (PD-1), programmed cell death ligand-1 (PD-L1), and cytotoxic T-lymphocyte-associated antigen 4 (CTLA-4)." (PMID 40040713, 2025). "CTLA4 rs231775 has also been associated with cancer risk either as predisposing or protective factor." (PMID 40862794, 2025). "HIF-1α also induces the expression of PD-L1 on cancer cells and cytotoxic T-lymphocyte-associated protein 4 (CTLA4) on CD8+ T-cells, which reduces T cell-mediated antitumor responses." (PMID 40072059, 2025). "In the context of cancer, induction and ligation of PD-1 and CTLA-4 are implicated in the development of T cell exhaustion and suppression of antitumor immunity." (PMID 40712021, 2025). "CTLA-4 is also associated with cancer cells, although the exact mechanism of this regulation is not fully understood." (PMID 40574024, 2025).
cancer (continued). "Some immune check-point inhibitors (ICIs) have been approved as cancer immunotherapy, because they target cytotoxic T lymphocyte-associated antigen 4 (CTLA4), programmed cell death protein 1 (PD-1) and its ligand PD-L1." (PMID 41339932, 2025). "These agents target immune checkpoints like cytotoxic T-lymphocyte-associated protein 4 (CTLA-4) and programmed cell death 1 or its ligand (PD-1/PD-L1), disrupting immunosuppressive pathways and immune homeostasis critical for cancer progression." (PMID 41278277, 2025). "Particularly ICIs targeting programmed cell death protein 1 (PD-1), its ligand PD-L1 or cytotoxic T lymphocyte-associated protein 4 (CTLA-4), have achieved extraordinary success in treating cancers such as non-small cell lung cancer (NSCLC)." (PMID 40274631, 2025). "In this population of anti-CTLA-4-treated patients, an association between additional irAEs and improved cancer outcomes was observed." (PMID 40563660, 2025). "Our data examining CTLA-4-directed ICI replicate findings where the development of the irAE is associated with improved cancer outcomes in PD-1 and PD-L1 ICI-treated patients." (PMID 40563660, 2025). "Recently, immune checkpoint blockade has become a promising strategy for cancer treatment, with monoclonal antibodies targeting programmed cell death protein 1 (PD- 1), PD-L1, and cytotoxic T-lymphocyte-associated protein 4 (CTLA-4)." (PMID 40496608, 2025). "ICIs, including inhibitors of programmed death-1 (PD-1), programmed death-ligand 1 (PD-L1), and cytotoxic T-lymphocyte-associated antigen 4 (CTLA-4), work by blocking the inhibitory signals that prevent T cells from attacking cancer cells." (PMID 41382107, 2025). "They block inhibitory signals, such as cytotoxic T lymphocyte-associated antigen-4 (CTLA4), enabling T cells to target cancer cells." (PMID 39937358, 2025). "ICI treatment is a common therapeutic approach in cancer, which mainly includes anti-programmed death-1/programmed death-ligand 1 (PD-1/PD-L1) and anti-cytotoxic T-lymphocyte-associated protein 4 (CTLA-4)." (PMID 41226461, 2025). "A phase II study assessed the effectiveness of combination immunotherapy with anti-cytotoxic T-lymphocyte-associated antigen 4 (CTLA-4) (ipilimumab) and anti-PD-1 (nivolumab) in patients with rare cancers, including advanced NETs, showing an ORR of 43%." (PMID 41375037, 2025). "The therapeutic targeting of inhibitory checkpoint molecules against CTL-associated protein 4 (CTLA-4), PD-1, and PD-L1 have led to profound clinical responses and have revolutionized the landscape of cancer immunotherapy across multiple cancer types." (PMID 39099201, 2024). "The discovery of programmed cell death-1 (PD-1 and its ligand, PD-L1) and cytotoxic T lymphocyte-associated protein 4 (CTLA-4) revolutionized cancer immunotherapy." (PMID 38543305, 2024). "The use of immune checkpoint inhibitors (ICI) such as programmed death 1 (PD-1) and cytotoxic T lymphocyte-associated antigen-4 (CTLA-4) has become one of the most promising approaches in the field of cancer therapy." (PMID 39138733, 2024). "Programmed cell death ligand 1 (PD-L1)/program cell death protein 1 (PD-1) and cytotoxic lymphocyte-associated antigen 4 (CTLA-4) inhibitors are two of the most common immunotherapy classes used in cancer therapeutics." (PMID 38248113, 2024). "By blocking these checkpoints, such as programmed cell death protein 1 (PD-1) and its ligand (PD-L1), or cytotoxic T-lymphocyte-associated protein 4 (CTLA-4), ICIs re-engage the immune system to attack cancer cells." (PMID 39335733, 2024). "Immune checkpoint inhibitors targeting programmed cell death protein 1/programmed death-ligand 1 and cytotoxic T-lymphocyte-associated protein 4 (CTLA-4) improve the survival of patients with refractory cancer." (PMID 39594611, 2024). "Four relevant studies with 572 cancer patients and 1023 controls were examined for the association between the CTLA-4 318T/C polymorphism and hematologic malignancy risk." (PMID 39464701, 2024).
cancer (continued). "ICIs, with their ability to block inhibitory pathways such as anti-programmed death-ligand 1 (PD-1/PD-L1) and cytotoxic T-lymphocyte-associated Protein 4 (CTLA-4), have emerged as a cornerstone of cancer immunotherapy." (PMID 38611049, 2024). "For cancer patients treated with CTLA-4 antibodies, GI toxicity is the most common cause of discontinuation." (PMID 39539626, 2024). "Immune checkpoint inhibitors, such as anti-PD-1 (programmed cell death protein 1) and anti-CTLA-4 (cytotoxic T-lymphocyte-associated protein 4) antibodies, work by blocking the checkpoints that cancer cells use to evade immune detection." (PMID 39534601, 2024). "This proline subsequently activates cancer-associated fibroblasts (CAFs), enhancing their expression of immune checkpoint molecules like PD-L1 and CTLA-4, thereby promoting immune suppression." (PMID 39450177, 2024). "Immunotherapy by blocking immune checkpoints programmed death/ligand (PD1/PDL1) and cytotoxic T-lymphocyte-associated protein 4(CTLA4) has emerged as new therapeutic targets in cancer." (PMID 38634058, 2024). "Antibodies targeting CTLA-4 (Cytotoxic T-lymphocyte associated protein-4), PD-1 (Programmed cell death protein 1), or its ligand PD-L1 (Programmed death-ligand 1), are used in various cancer therapies." (PMID 38786018, 2024). "Twelve relevant studies with 1575 cancer patients and 2172 controls were examined for the association between the CTLA-4 49A/G polymorphism and hematologic malignancy risk." (PMID 39464701, 2024). "The CD86-CTLA4 interaction is also implicated in T cell response inhibition, and CTLA4 blockade is considered to be a promising approach in cancer immunotherapy." (PMID 38890370, 2024). "Inhibiting the cytotoxic T-lymphocyte-associated protein-4 (CTLA-4)-mediated immune checkpoint system using an anti-CTLA-4 antibody (Ab) can suppress the growth of various cancers, but the detailed mechanisms are unclear." (PMID 39106430, 2024). "The first immune checkpoint to be identified in treating cancer was cytotoxic T lymphocyte-associated protein 4 (CTLA-4), which competes with the costimulatory molecule CD28 for ligands CD80 and/or CD86 (collectively known as B7 ligands)." (PMID 38732242, 2024). "The +49A/G polymorphism was associated with an increased risk of cancer in Asians but was associated with an decreased cancer risk in Caucasians, while the CTLA-4 319C/T polymorphism was associated with a notable decreased cancer risk in Caucasians." (PMID 39464701, 2024). "Five relevant studies with 753 cancer patients and 1223 controls were examined for the association between the CTLA-4 60A/G polymorphism and hematologic malignancy risk." (PMID 39464701, 2024). "Immune checkpoint inhibitors target proteins such as programmed cell death protein 1 (PD-1) and cytotoxic T-lymphocyte-associated protein 4 (CTLA-4) to enhance the immune response against cancer cells." (PMID 38474377, 2024). "For example, proteins like programmed cell death protein 1 (PD-1), its ligand (PD-L1), and CTLA-4 (cytotoxic T-lymphocyte-associated protein 4) are exploited by cancer cells to evade the immune system." (PMID 38831199, 2024). "Programmed cell death protein (PD-1) and cytotoxic T-lymphocyte-associated protein 4 (CTLA-4) are the two most extensively studied immune checkpoint molecules that are exploited by cancer cells to evade immune surveillance." (PMID 39403602, 2024). "In this comprehensive review, we delve into the biological mechanisms underlying the most frequently targeted ICPs in cancer therapy, including CTLA-4, PD-1, PDL-1, and LAG3." (PMID 39359534, 2024). "Immune checkpoint inhibitors (ICIs) targeting cytotoxic T-lymphocyte-associated antigen-4 (CTLA-4), programmed cell death-1 (PD-1), and PD ligand 1 (PD-L1) have become the standard of care for several cancer types." (PMID 39451777, 2024).
cancer (continued). "The development of immune checkpoint inhibitors, especially monoclonal antibodies that target vital proteins like programmed death receptor 1 (PD-1) and cytotoxic lymphocyte-associated protein 4 (CTLA-4), has revolutionized the treatment of cancer." (PMID 38931856, 2024). "Recently, immune checkpoint inhibitors, such as antibodies against programmed death-1 (PD-1), programmed death-ligand 1 (PD-L1), and cytotoxic T lymphocyte-associated antigen 4 (CTLA-4), have greatly improved cancer treatment." (PMID 38983267, 2024). "Contrary to traditional anti-inflammatory therapies such as corticosteroids and non-specific immunosuppressants that bear the risk of cancer recurrence, the anti-CTLA4 treatment seems to have a dual beneficial effect for cancer patients." (PMID 39737964, 2024). "Two well-known immune checkpoints in cancer are cytotoxic T-lymphocyte-associated protein 4 (CTLA-4) and programmed cell death protein 1 (PD-1)." (PMID 39445021, 2024). "Four relevant studies with 569 cancer patients and 811 controls were examined for the association between the CTLA-4 1661A/G polymorphism and hematologic malignancy risk." (PMID 39464701, 2024). "Treatment of cancer patients with CTLA-4-based therapy is therefore associated with eczematous dermatitis occurrence." (PMID 39795946, 2024). "From a therapeutic angle, with the increasing use of immune checkpoint inhibitors in cancer treatment, understanding how specific mutations can affect the function of receptors like CTLA-4 is critical." (PMID 38542966, 2024). "CTLA-4 prevents T cells from destroying other cells, particularly cancer cells, when associated with the B7 protein." (PMID 38533510, 2024). "Immune checkpoint inhibitors (ICIs) (such as cytotoxic T-lymphocyte-associated protein 4 (CTLA-4), programmed cell death-1 (PD-1), and PD-L1 inhibitors) have emerged as important strategies for various cancers." (PMID 39351236, 2024). "Immune checkpoint inhibitors (ICIs), such as cytotoxic T lymphocyte-associated antigen 4 (CTLA-4), programmed death-1 (PD-1), and its ligand (PD-L1), represent a breakthrough in cancer treatment that successfully increases the survival rate of the patients." (PMID 39133693, 2024). "Immune checkpoint inhibitors, such as anti-cytotoxic T-lymphocyte-associated protein-4 (CTLA-4) antibodies (Abs), have been attracting attention as breakthrough anti-cancer therapies in recent years." (PMID 39106430, 2024). "Immune checkpoint pathways, such as the programmed cell death protein 1 (PD-1) and cytotoxic T-lymphocyte-associated protein 4 (CTLA-4) pathways, regulate the activity of T cells and their responses to cancer cells." (PMID 39001539, 2024). "Common checkpoint proteins in immunotherapy include PD-1 (programmed death-1), PD-L1 (programmed death ligand-1) and CTLA-4 (cytotoxic T-lymphocyte associated protein 4), which block the immune cells to attack cancer cells." (PMID 39247188, 2024). "Inhibitory programmed cell death 1/programmed cell death ligand 1 or cytotoxic T-lymphocyte-associated protein 4 pathways allow malignant tumors to evade the immune system." (PMID 38562964, 2024). "The success of ICB in cancer treatment relies primarily on programmed cell death protein 1 (PD-1) and cytotoxic T-lymphocyte-associated protein 4 (CTLA-4)." (PMID 38785930, 2024). "Further investigation into the correlation between NOX4 expression and immune checkpoint genes across 40 cancer types revealed a close association with common immune checkpoints, such as PD-L1 and CTLA-4." (PMID 38663913, 2024). "Cytotoxic T lymphocyte-associated antigen 4 (CTLA-4, also known as CD152), identified by Brunet JF in 1987, is the first co-inhibitory molecules for cancer immunotherapy." (PMID 38257366, 2024). "Further investigations are warranted to elucidate the risk of HZ in patients with different cancer types and those receiving treatment with other types of ICIs such as anti-CTLA-4, anti-LAG-3, and anti-TIM-3 inhibitors." (PMID 38672581, 2024).
cancer (continued). "Cytotoxic T lymphocyte-associated protein 4 (CTLA-4) is another important immune checkpoint that has recently emerged as a target for cancer immunotherapy." (PMID 39323561, 2024). "Anti-programmed cell death-1 (PD-1) and anti-cytotoxic T lymphocyte-associated antigen-4 (CTLA-4) monoclonal antibodies are two main types of widely used ICBs that drastically improve the survival and prognosis of many patients with cancer." (PMID 39062019, 2024). "First, we directed our focus towards the investigation of genetic mutations in the cytoplasmic domain of CTLA-4 associated with cancer." (PMID 38542966, 2024). "These agents work by blocking specific proteins on immune cells, such as programmed cell death protein 1 (PD-1), programmed death-ligand 1 (PD-L1), and cytotoxic T-lymphocyte-associated protein 4 (CTLA-4), which cancer cells exploit to evade immune detection." (PMID 39553010, 2024). "These drugs inhibit proteins such as programmed cell death protein-1 (PD-1) and cytotoxic T-lymphocyte-associated protein 4 (CTLA-4), which are used by cancer cells to evade immune recognition." (PMID 39337925, 2024). "ICIs are antibodies against the immune checkpoint molecules Cytotoxic T-Lymphocyte-Associated Antigen 4 (CTLA-4) and Programed Death Ligand 1 (PD-L1), preventing cancer cells from deactivating T-cells." (PMID 39451258, 2024). "Ipilimumab interacts with the inhibitory cytotoxic T-lymphocyte-associated protein 4 (CTLA-4) at the cell surface, thereby releasing the inhibition of the immune response and effectively exposing the cancer cells to attack." (PMID 39594689, 2024). "Two relevant studies with 365 cancer patients and 700 controls were examined for the association between the CTLA-4 319C/T polymorphism and hematologic malignancy risk." (PMID 39464701, 2024). "The first dual IO-combination that was tested across multiple cancer types was anti-PD1 combined with antibodies against cytotoxic T lymphocyte associated protein-4 (CTLA4)." (PMID 37079257, 2023). "Checkpoint inhibitors for the programmed cell death protein 1 (PD-1/PD-L1) and cytotoxic T-lymphocyte-associated protein 4 (CTLA-4) pathways have been developed for the treatment of cancer." (PMID 37817020, 2023). "Immune checkpoint inhibitor therapy (ICT), targeting cytotoxic T-lymphocyte–associated-antigen-4 (CTLA-4) and/or programmed cell death protein 1 (PD-1), results in durable remissions in patients with previously incurable cancers." (PMID 36867675, 2023). "Considering its role in maintaining immunological balance, genetic variants in CTLA4 have the potential to modify the immune response and, susceptibility to cancer development." (PMID 37601778, 2023). "For example, the monoclonal antibodies ipilimumab and tremelimumab have been recently applied for the CTLA-4 blocking strategy which results in the growth of blood cells in the immune system causing cancer cells death." (PMID 36109471, 2023). "Immune modulating antibodies or checkpoint inhibitors most commonly target the cytotoxic T-lymphocyte associated protein 4 (CTLA-4) or PD-1/PD-L1 ligand as the cancer cells display these ligands on their cell surface." (PMID 38005965, 2023). "We have found only one gene related to anti-CTLA-4 resistance: BLCAP or Bladder Cancer Associated Protein." (PMID 37055532, 2023). "The first successes involved Programmed-death 1(PD-1)/Programmed-Death ligand 1 (PD-L1) and cytotoxic T-lymphocyte-associated protein 4 (CTLA-4) pathways which are crucial mediators of cancer cells evasion from antitumoral T-cell-mediated cytotoxicity." (PMID 38164130, 2023). "Immune checkpoint inhibitors targeting programmed cell death protein-1 (PD-1), its ligand (PD-L1), cytotoxic T-lymphocyte associated protein-4 (CTLA-4) or lymphocyte activation gene-3 have improved the survival of patients with multiple cancer types." (PMID 37964379, 2023). "We found that most of the genes were risk factors in several cancers, except for CTLA4, KCNQ1, and GLS2." (PMID 36860371, 2023).